OGG1 (8-oxoguanine DNA glycosylase)
Diseases named in the same sentence as OGG1 in open-access papers (continued):
Sharing a sentence is not in itself a finding about the gene and the disease.
lung adenoma (3 papers, 2017 to 2022). A benign, well circumscribed epithelial neoplasm that arises from the bronchus or the lung parenchyma. "Furthermore, incidences of lung adenomas were significantly elevated in both Ogg1−/− males and females as compared with respective Ogg1−/− control and DMBDD-treated Ogg1+/+ groups." (PMID 28820464, 2017). "Furthermore, lung adenomas were detected in both PB-treated and control Ogg1−/− mice." (PMID 28785378, 2017).
lupus nephritis (3 papers, 2015 to 2021). Glomerulonephritis in the context of systemic lupus erythematosus. "For example, the OGG1 SNP rs1052133 is associated with the development of lupus nephritis and an observed increase of 8-OH-dG levels in plasma." (PMID 33072095, 2020). "OGG1 polymorphism could offer susceptibility to lupus nephritis and modulate 8-OH-d G serum level in SLE patients." (PMID 34442337, 2021). "A single nucleotide polymorphism (SNP) in OGG1 is associated with development of lupus nephritis." (PMID 33072095, 2020).
oral cancer (3 papers, 2022). "We found that OGG1 protein expression is increased upon cisplatin, H2O2 treatment, or Lon overexpression in oral cancer cells, suggesting that cisplatin/Lon causes oxidative damage in mtDNA." (PMID 35296653, 2022). "Since the 8-OHdG is repaired by 8-oxoguanine glycosylase (OGG1), it warrants a detailed assessment of DNA repair systems such as OGG1 of the UVC/SK2-treated oral cancer cells." (PMID 35625933, 2022).
rectal cancer (3 papers, 2008 to 2021). A primary or metastatic malignant neoplasm that affects the rectum. "We report on a germline genetic polymorphism in OGG1 resulting in the missense mutation Ser326Cys, strongly affecting outcome upon multimodal treatment of rectal cancer." (PMID 34199885, 2021). "Thus, further investigations, at best in a prospective clinical fashion, are necessary to confirm whether the OGG1 rs1052133 polymorphism is a relevant prognostic biomarker in locally advanced rectal cancer treated in a multimodal fashion." (PMID 34199885, 2021).
Sepsis (3 papers, 2014 to 2021). Sepsis is defined as life-threatening organ dysfunction caused by a dysregulated host response to infection. "We previously found an important role for OGG1 in mtDNA 8-OHdG removal in the liver during sepsis and associated its gene transcription with the regulation of nuclear genes required for mitochondrial biogenesis." (PMID 24988481, 2014). "Expression of OGG1, the primary enzyme responsible for the excision of 8-oxoG, was downregulated in patients with sepsis (p < 0.005)." (PMID 33494815, 2021). "Although PGC-1a induction has not been previously shown to be linked to mtDNA repair, it is possible that PGC-1ainduction may lead to increase in OGG1, resulting in increased mtDNA repair, and renal protection against oxidative stress in sepsis." (PMID 24988481, 2014). "Due to the significant early renal oxidative damage observed during sepsis, we examined changes in the mtDNA base-excision repair enzymes, Ogg1 mRNA and OGG1 protein expression in the kidney as well as UDG, another mitochondrial DNA repair enzyme, protein expression." (PMID 24988481, 2014). "The Western blot analysis showed that sepsis reduced their contents about 48% in POLG, 26% in AP-endoneclease, 11% in OGG1 and 25% in UNG1." (PMID 26448624, 2015). "To explore whether sepsis-AKI leads to oxidation of DNA, we performed an 8-oxoG staining and quantified the expression of the base-excision repair enzyme 8-oxoguanine DNA glycosylase (OGG1) in kidney biopsy material." (PMID 33494815, 2021).
systemic lupus erythematosus (3 papers, 2015 to 2023). An autoimmune multi-organ disease typically associated with vasculopathy and autoantibody production. "To determine the effect of Ogg1-deficiency on glomerulonephritis in this model of lupus, we measured proteinuria." (PMID 33072095, 2020). "This demonstrates the importance of oxidized DNA repair enzyme OGG1 in protecting against oxidized DNA-induced IFN responses in lupus." (PMID 33072095, 2020). "In this study, we explored the contribution of OGG1 to the pathogenesis of pristane-induced lupus." (PMID 33072095, 2020).
thyroid (3 papers, 2021 to 2024). "For example, 8-oxo guanine-DNA glycosylase (OGG1) had cross-regulation with the ErbB pathway in thyroid physiopathology." (PMID 38654239, 2024). "Overall, this study suggests further investigation of the pathophysiological interactions of OGG1-BER pathways to elucidate the mechanisms underlying the onset and development of thyroid diseases." (PMID 35269445, 2022). "Our data on OGG1 protein expression suggest that it was physiologically regulated in response to oxidative modulation of ErbB, and that these might be dysregulated in the signaling pathway involving AKT in the progression of thyroid malignancies with RET/PTC rearrangements." (PMID 35269445, 2022).
triple-negative breast carcinoma (3 papers, 2012 to 2022). An invasive breast carcinoma which is negative for expression of estrogen receptor (ER), progesterone receptor (PR), and human epidermal growth factor receptor 2 (HER2). "Knocking out BRCA1 in triple-negative breast cancer cell lines causes hypersensitivity to the OGG1 inhibitor TH5487." (PMID 35619904, 2022). "Here, we show that the knockout of BRCA1 in triple-negative breast cancer (TNBC) cell lines increases their sensitivity to the OGG1 inhibitor TH5487, reflecting a possible synthetic lethal relationship between the two genes." (PMID 35619904, 2022).
type 1 diabetes (3 papers, 2010 to 2023). "Despite an increase in Ogg1 protein levels, the study revealed significantly lower cardiac Ogg1 activity in mice with type 1 diabetes compared with the comparison group." (PMID 38116061, 2023).
angiomyolipoma (2 papers, 2009). A neoplasm with perivascular epithelioid cell differentiation often associated with tuberous sclerosis. "To determine if the decrease in OGG1 is associated with 8-oxodG accumulation in angiomyolipomas, we quantified 8-oxodG by HPLC in control and tumor kidney samples." (PMID 19265534, 2009). "In this study, we demonstrate that 8-OxodG accumulates in angiomyolipomas tissue compared to normal tissue suggesting the deficiency of DNA repair OGG1." (PMID 19265534, 2009). "Our data show that the increase in tuberin phosphorylation and the deficiency in tuberin expression are associated with decreased protein and mRNA expression of OGG1 in angiomyolipomas kidney tissue from TSC patients." (PMID 19265534, 2009). "We now find that decrease in tuberin protein expression in angiomyolipomas tissues is associated with a decrease in protein and mRNA expression of OGG1." (PMID 19265534, 2009). "Therefore, the antimutator function of OGG1 protein portrays OGG1 as a strong susceptibility candidate gene for tumors including angiomyolipoma." (PMID 19265534, 2009). "The decrease in OGG1 mRNA in angiomyolipoma tissue suggests that decreased transcription is one potential mechanism responsible for downregulation of OGG1 protein." (PMID 19265534, 2009). "In this study, NF-YA expression is decreased in angiomyolipoma tissue compared to control tissue suggesting that the decrease in OGG1 protein is due to decreased transcription." (PMID 19265534, 2009). "In addition, tuberin deficiency is associated with downregulation of protein and mRNA expression of OGG1 as well as NF-YA expression and accumulation of 8-oxodG in angiomyolipoma kidney tissue of TSC patients." (PMID 20040097, 2009).
breast tumor (2 papers, 2013 to 2015). "To examine whether E2-mediated suppression of OGG1 was tissue specific, we performed western blot analyses with protein samples from liver, kidney, uterus, lung, spleen, breast and breast tumor tissues from female ACI rats treated with E2 for 240 days." (PMID 23697596, 2013).
Cerebral ischemia (2 papers, 2019 to 2025). Restriction of arterial blood supply to the brain associated with insufficient oxygenation to support the metabolic requirements of the tissue. "A study reported that the OGG1 peptide and its activity exhibited a significant increase following 90 min of cerebral ischemia and 20–30 min of reperfusion in murine models." (PMID 40867876, 2025).
chronic kidney disease (2 papers, 2022 to 2025). Impairment of the renal function secondary to chronic kidney damage persisting for three or more months. "OGG1 promotes fibrosis progression in chronic kidney disease by interacting with Smad7 to promote TGF-β1-induced cell transformation." (PMID 36620083, 2022).
Cockayne syndrome (2 papers, 2009 to 2022). A multisystem condition characterized by short stature, a characteristic facial appearance, premature aging, photosensitivity, progressive neurological dysfunction, and intellectual deficit. "An 8OG lesion in a TS might also be repaired by pathways other than OGG1-mediated BER, possibly including TCR, as cells from patients with Cockayne syndrome have been shown to be defective for both TCR and the repair of oxidative lesions." (PMID 19629170, 2009).
differentiated thyroid carcinoma (2 papers, 2022 to 2025). Differentiated thyroid carcinoma (DTC), also known as papillary or follicular thyroid carcinoma, is a slow-growing malignancy usually presenting in adults as an asymptomatic thyroid mass. "Therefore, it would be very interesting to further investigate these functional aspects of OGG1 in papillary thyroid carcinoma with RET/TPC rearrangements." (PMID 35269445, 2022).
endothelial dysfunction (2 papers, 2024 to 2025). In vascular diseases, endothelial dysfunction is a systemic pathological state of the endothelium (the inner lining of blood vessels) and can be broadly defined as an imbalance between vasodilating and vasoconstricting substances produced by (or acting on) the endothelium. "These compensatory mechanisms and the oxidative stress markers OGG1, MPG, and ADMA (a marker of endothelial dysfunction) appear to be stimulated mainly by metabolic disturbances associated with a rapid change in diet, even if the change involves a return to a balanced diet." (PMID 38396961, 2024).
Glucose intolerance (2 papers, 2021 to 2024). Glucose intolerance (GI) can be defined as dysglycemia that comprises both prediabetes and diabetes. "Ogg1−/− mice display increased adipose mass along with significant increases in hepatic and serum lipids, concomitant with marked glucose intolerance, skeletal muscle atrophy, and adipocyte inflammation." (PMID 33503804, 2021).
hepatocellular adenoma (2 papers, 2017). A benign epithelial neoplasm arising from the hepatocytes. "In the liver of Ogg1 knockout and wild type mice, DMBDD treatment caused development of putative preneoplastic foci of mostly basophilic phenotype, hepatocellular adenomas (HCAs), hemangiomas and hemangiosarcomas." (PMID 28820464, 2017). "Incidence of total liver tumors (hepatocellular adenomas, hemangiomas and hemangiosarcomas) was significantly higher in the DMBDD-administered Ogg1−/− males and females." (PMID 28820464, 2017).
hyper-keratosis (2 papers, 2006 to 2020). "In females, the association between hyper-keratosis and OGG1 expression showed some evidence of a dose-dependent increased risk in the first three quartile groups, although the trend was not statistically significant (p = 0.22)." (PMID 16759981, 2006). "Histopathological analysis of H&E stained sections revealed epidermal hyperplasia, consisting of acanthosis and hyperkeratosis, in pristane-treated Ogg1−/− mice." (PMID 33072095, 2020). "Males in the highest OGG1 expression category (OGG1, 2.02–4.37) experienced hyperkeratosis nearly three times more frequently than those in the lowest category [odds ratio (OR) = 2.98, p = 0.047]." (PMID 16759981, 2006).
infertile (2 papers, 2021 to 2024). "In this study, the effects of OGG1 Ser326Cys polymorphism in semen oxidative DNA damage were evaluated in a population of males with infertility." (PMID 39457598, 2024). "In this study, the OGG1 Ser326Cys polymorphism in the semen of a group of infertile men and its effect on DNA oxidation were evaluated." (PMID 39457598, 2024). "In this study, OGG1 Ser326Cys polymorphism was evaluated in a population of 118 men selected during infertility consultations." (PMID 39457598, 2024). "In this study, the OGG1 Ser326Cys polymorphism and its effect on DNA oxidation were evaluated in 118 infertile men." (PMID 39457598, 2024). "Previous studies have shown that the Cys326 OGG1 allele has a higher incidence in infertile men compared to fertile men in Asian and Spanish populations." (PMID 39457598, 2024). "Reports that included infertile subjects with fertile subjects as controls in Chinese, Taiwanese, and Spanish populations found a higher incidence of men carrying the Cys326 OGG1 allele in the infertile groups compared to the fertile groups." (PMID 39457598, 2024).
ischemia (2 papers, 2012 to 2023). A hypoperfusion of the BLOOD through an organ or tissue caused by a PATHOLOGIC CONSTRICTION or obstruction of its BLOOD VESSELS, or an absence of BLOOD CIRCULATION. "From this it seems that OGG1 plays a role in reducing brain damage and improving functional outcome after ischemia by repairing oxidatively damaged nuclear DNA." (PMID 23203191, 2012).
male infertility (2 papers, 2013 to 2022). The inability of the male to effect fertilization of an ovum after a specified period of unprotected intercourse. "Since it was shown that human APE1 enhances the activity of OGG1 to remove 8-oxodG it is possible that DNA integrity of spermatozoa may be exceptionally dependent on OGG1 and the decrease in its activity may contribute to abnormal spermatozoa and male infertility." (PMID 23874641, 2013).
multiple sclerosis (2 papers, 2023 to 2025). A progressive autoimmune disorder affecting the central nervous system resulting in demyelination. "In multiple sclerosis (MS), vitamin D3 influences immune regulation by decreasing pro-inflammatory cytokines (e.g., IL-17, Th1, Th9, Th22 responses) while enhancing DNA repair and antioxidant capacity via pathways such as OGG1, MYH, MTH1, and NRF2." (PMID 41156455, 2025).
T cell lymphoma (2 papers, 2014 to 2017). "One DMBDD-treated female Ogg1+/+ mouse developed T cell lymphoma, likely due to the MNU treatment, as previously reported in C57Bl/6J mice, but in our study no such thymic lymphomas were observed in Ogg1−/− mice." (PMID 28820464, 2017). "One Ogg1+/+ female mouse in DMBDD group developed T cell lymphoma (5%)." (PMID 28820464, 2017). "The OGG1 326 GG and BRCA1 871 TT genotypes were associated with a decreased risk for NHL (OROGG1 GG = 0.70, p = 0.008; ORBRCA1 TT = 0.71, p = 0.048), DLBCL (OROGG1 GG = 0.68, p = 0.02; ORBRCA1 TT = 0.62, p = 0.04), and T-cell lymphoma (OROGG1 GG = 0.59, p = 0.04; ORBRCA1 TT = 0.42, p = 0.04)." (PMID 24756092, 2014).
thyroid cancer (2 papers, 2017 to 2024). "The rs1052133 polymorphism in the OGG1 gene may therefore have a limited impact on the risk of thyroid cancer, but its role in the DNA repair pathway requires further research." (PMID 38892180, 2024). "It is necessary to mention, that no increased risk of thyroid cancer in DMBDD-treated Ogg1 knockout mice was found in this study." (PMID 28820464, 2017).
tuberous sclerosis (2 papers, 2009 to 2022). Hereditary disease characterized by seizures, intellectual disability, developmental delay, and skin and ocular lesions. "In the kidneys of patients with tuberous sclerosis, loss of a protein encoded by tuberous sclerosis complex 2 (Tsc2) can downregulate OGG1 protein expression by regulating transcription factor AP4 binding to the OGG1 promoter, thereby increasing the incidence of tumors." (PMID 36620083, 2022).
ulcerative colitis (2 papers, 2012 to 2020). An inflammatory bowel disease involving the mucosal surface of the large intestine and rectum. "This study also showed evidence of increased ulcerative colitis, thus suggesting that deficiencies in OGG1 can have either protective or sensitizing effects on disease outcomes depending on the organ system under investigation." (PMID 31935236, 2020).
Zinc deficiency (2 papers, 2017 to 2021). A deficiency of the essential metal Zinc; an essential cofactor for many enzymes. "Significant changes in RNA expression of genes that regulate zinc homeostasis, response to oxidative stress and insulin production (including zip1, znt7, nrf2, ogg1, pax4, and insa) were found in zinc deficient, or zinc deficiency and arsenic exposed embryos." (PMID 28837703, 2017). "Here we show in the zebrafish embryo that zinc deficiency was associated with the suppression of several genes that respond to oxidative stress (nrf2a, nrf2b, mt2, and ogg1) at the mRNA level." (PMID 28837703, 2017). "In contrast, Ogg1 protein has been shown to be induced with zinc deficiency in adult rat livers." (PMID 28837703, 2017). "Modest, but significant effects of zinc deficiency and/or arsenic exposure were also found in developing embryos on the expression of genes that regulate zinc transport, response to oxidative stress, and insulin production (including zip1, znt7, nrf2, ogg1, pax4, and insa)." (PMID 28837703, 2017).
age (1 paper, 2016). A temporal measurement of the time period elapsed since an identifiable point in the life cycle of an organism. "Evidences have identified the correlation of 8-oxoguanine DNA glycosylase-1 (OGG1) and eph-receptor tyrosine kinase-type A2 (EPHA2) polymorphisms in age-related cataract (ARC) risk." (PMID 27681698, 2016).
airway hyperresponsiveness (1 paper, 2016). "Whole-genome expression analyses suggest a cellular response to OGG1-BER, involving genes that may have a role in the pathophysiology of EIA leading to mast cell degranulation, airway hyperresponsiveness, and bronchoconstriction." (PMID 27524866, 2016).
allergic asthma (1 paper, 2022). A asthma with a basis in a pathological type I hypersensitivity reaction. "Together, these results suggest a potential role for OGG1 as a target to treat allergic asthma." (PMID 36324676, 2022). "Collectively, our findings display OGG1 inhibition by TH5487 as a novel, potent pharmacological approach to treat allergic asthma." (PMID 36324676, 2022).
behavioural disorders (1 paper, 2023). "Prenatal exposure to the ROS-enhancing drug EtOH was similarly associated with OGG1-dependent changes in epigenetic marks in the fetal brain, but with different patterns than with saline and more extensive behavioural disorders." (PMID 37759530, 2023).
bronchiolitis (1 paper, 2023). Inflammation of the bronchioles characterized by swelling of the bronchioles and mucus accumulation. "In a mouse model of bronchiolitis induced by RSV infection, functional ablation of OGG1 by a small molecule inhibitor (TH5487) enhances IFN-λ production, decreases immunopathology, neutrophilia, and confers antiviral protection." (PMID 37600772, 2023).
cardia (1 paper, 2017). "Immunohistochemical expressions in diffuse-type adenocarcinoma of gastric cardia showed lower expression of OGG1, which related to higher T-stage, lymphatic invasion, and lymph node metastasis." (PMID 28415770, 2017).
cervical squamous cell carcinoma (1 paper, 2023). A squamous cell carcinoma arising from the cervical epithelium. "The results showed that compared with the control group of cervical squamous cell carcinoma SiHa cells, the expression of differential proteins PCNA, ATM, LIG1 and HMGB1 in Ect1/E6E7 cells decreased significantly, while the expression of TDG and OGG1 proteins increased significantly." (PMID 36726132, 2023).
Chagas disease (1 paper, 2012). A parasitic infection caused by Trypanosoma cruzi. "In this report, we identified and characterized Ogg1 from the protozoan parasite Trypanosoma cruzi (TcOgg1), the causative agent of Chagas disease." (PMID 22876325, 2012).